ING3 (inhibitor of growth family member 3)
Diseases named in the same sentence as ING3 in open-access papers (continued):
Sharing a sentence is not in itself a finding about the gene and the disease.
cancer (16 papers, 2016 to 2025). A tumor composed of atypical neoplastic, often pleomorphic cells that invade other tissues. "Although previous investigations have reported a loss of ING3 expression in small sample number studies, we found, using the cBioPortal, that INGs are broadly amplified in a variety of cancers." (PMID 33925563, 2021). "Splice variants of ING3 have not yet been analysed in detail, and therefore, it is unclear what contributions full-length and ING3 splice variants have in cancer proliferation and EMT." (PMID 34439818, 2021). "Ing3 deficiency in mice is early embryonal lethal, and thus, the role in cancer remains unclear." (PMID 34685579, 2021). "ING3 is frequently downregulated in different cancer types, such as head and neck carcinoma, melanoma, and hepatocellular carcinoma." (PMID 34439818, 2021). "This suggests that the ING3 protein levels in PC must be balanced in order to allow cancer cells to proliferate." (PMID 34685579, 2021). "Nevertheless, a conditional knockout mouse, together with the constitutive Ing3 insertional mutant and the conditional Ing3 transgenic mouse will provide valuable tools for further analyzing the functions of ING3 in in vivo cancer models." (PMID 31905726, 2019). "We have so far demonstrated that ING3 is required for the expression of an intricate transcriptional network involved in regulating the proliferation of cancer cells." (PMID 29381681, 2018). "Then, we measured ING3 levels in benign tissues compared with matched cancer samples and found that elevated ING3 levels correlate with treatment resistance and poor survival, corroborating in vitro assays suggesting that ING3 has oncogenic properties." (PMID 29381681, 2018). "In agreement with ING4 and ING5 being required for normal cell cycle progression, we observed that ING3 is also required for cellular proliferation of cancer cells." (PMID 29381681, 2018). "In agreement, we have found elevated levels of ING3 in various cancers and using an ex vivo human tissue explant model demonstrated that ING3 does have oncogenic properties by stimulating cellular proliferation." (PMID 29381681, 2018). "Negative control of the cell cycle after overexpression of ING1 or ING2 in U2OS or normal skin fibroblast cells is consistent with the observations of overexpression of ING3 in cancer cells given their opposite involvements in HDAC and HAT complexes, respectively." (PMID 31905726, 2019). "Importantly, elevated ING3 expression in cancer patients and correlation with poor survival support ING3 as a biomarker and potentially a therapeutic target in both early and advanced treatment-resistant cancer patients." (PMID 29381681, 2018). "Importantly, ING3 elevated copy number and protein levels in cancer patients, particularly in treatment-resistant patients, designate ING3 as a novel marker of poor survival for cancer patients and an unsuspected oncoprotein." (PMID 29381681, 2018). "The ING3 tumor suppressor protein contains a plant homeodomain (PHD) that reads the epigenetic code via recognition of histone H3 tri-methylated at lysine 4 (H3K4me3), and this domain is lost or mutated in various human cancers." (PMID 27281824, 2016). "Four riboSNitch-depleted 5′UTRs (ING3, RBM22, NSA2 and TAF2) were detected at the q-value cutoff of 0.05, and all of these elements were cancer-specific." (PMID 31160636, 2019).
cancer (continued). "In agreement with the requirement of TIP60 for cellular proliferation, we observed that ING3 was also essential for the proliferation of human breast (MCF7) and prostate (LNCaP, PC3) cancer cell lines, suggesting a central role for the ING3/TIP60 complex in cell cycle progression." (PMID 33925563, 2021). "In a recent screening study, it was noted that high ING3 levels correlate with worse prognosis in patients with erythroblast transformation-specific-related gene (ERG) negative PC, and that a ten-gene signature that correlates with patient survival in these cancers included ING3." (PMID 28511652, 2017).
ING3 also shares sentences with these, for which no sentence is quoted: cutaneous melanoma (3 papers); prostate tumor (3); colorectal cancer (2); autism spectrum disorder (1); cardiac hypertrophy (1); glioblastoma (1); glioma (1); myeloma (1); ovarian carcinoma (1); Potocki-Shaffer syndrome (1); prostate intraepithelial neoplasia (1).